ALKBH5 (alkB homolog 5, RNA demethylase)
Diseases named in the same sentence as ALKBH5 in open-access papers (continued):
Sharing a sentence is not in itself a finding about the gene and the disease.
presbycusis (1 paper, 2025). Bilateral hearing loss caused by progressive degeneration of cochlear structures and central auditory pathways, typically associated with the aging process. "ALKBH5 and YTHDC1 emerge as promising biomarkers, presenting a potential pathway for diagnosing presbycusis." (PMID 40198960, 2025).
psoriasis (1 paper, 2025). An autoimmune condition characterized by red, well-delineated plaques with silvery scales that are usually on the extensor surfaces and scalp. "To investigate the role of N6‐methyladenosine (m6A) in psoriatic pathogenesis, we initially utilized Alkbh5 knockout (Alkbh5 KO) mice within the IMQ‐induced model of psoriasis." (PMID 40679079, 2025). "The Alkbh5 KO mice also displayed elevated levels of inflammatory cytokines, a characteristic of psoriasis." (PMID 40679079, 2025). "Conditional knockout of Mettl3 in macrophages alleviated psoriasis‐like symptoms in mice, whereas knockout of Alkbh5 exacerbated them." (PMID 40679079, 2025). "Interestingly, genes with differential m6A modification in Mettl3 cKO and Alkbh5 cKO relative to WT were enriched in psoriasis‐related pathways, including JAK‐STAT signaling pathway, Th17 cell differentiation, and Interleukin‐1 beta production." (PMID 40679079, 2025). "We next investigated the clinical relevance of the METTL3/ALKBH5‐m6A‐SLC15A3 axis in psoriasis." (PMID 40679079, 2025).
pulmonary tuberculosis (1 paper, 2022). A bacterial infection that affects the lungs and is caused by Mycobacterium tuberculosis. "The m6A methylation was involved in the pathogenesis of pulmonary tuberculosis (PTB), and our study aimed to reveal the potential association of m6A demethylase (ALKBH5, FTO) genes variation, expression levels and PTB." (PMID 36619747, 2022).
radiation pneumonitis (1 paper, 2023). Inflammation of the lung due to harmful effects of ionizing or non-ionizing radiation. "Radiation‐induced ALKBH5 mediated m6A demethylation of IL‐6 mRNA and reduced IL‐6 production to alleviate radiation pneumonitis." (PMID 36792369, 2023).
rectal tumors (1 paper, 2021). "The significant up-regulation of YTHDF1, YTHDF2, and METTL3, and down-regulation of ALKBH5, YTHDC2, and METTL14 could be observed in the 6 rectal tumors (P < 0.05), indicating that these m6A regulators may be associated with progression of RC." (PMID 34149792, 2021).
Rotavirus infection (1 paper, 2022). Infection with any of the rotaviruses. "We found that rotavirus infection induced global m6A modifications on mRNA transcripts by downregulating the m6a eraser ALKBH5." (PMID 35098923, 2022).
schizophrenia (1 paper, 2023). A major psychotic disorder characterized by abnormalities in the perception or expression of reality. "Overall, HTR1B, Arc, and ALKBH5 levels were increased in schizophrenia and positively associated with ERVWE1." (PMID 37990254, 2023). "ALKBH5 was a new risk gene for schizophrenia, and it is significantly related to HTR1B in schizophrenia patients." (PMID 37990254, 2023). "Further analysis revealed that ALKBH5 was a possible independent risk factor for schizophrenia." (PMID 37990254, 2023). "Importantly, further analysis revealed that ALKBH5 was an independent risk factor for schizophrenia." (PMID 37990254, 2023). "Additionally, the univariate and multivariate analyses showed that ALKBH5 was an independent risk factor for schizophrenia." (PMID 37990254, 2023). "Further analyses confirmed that ALKBH5 may be an independent risk factor for schizophrenia." (PMID 37990254, 2023). "Subsequent analysis revealed several positive correlations between ERVWE1 and HTR1B (p = 0.01, r = 0.65), Arc (p = 0.03, r = 0.57), and ALKBH5 (p < 0.01, r = 0.78) in the mRNA levels of schizophrenia patients, as determined by Spearman's correlation." (PMID 37990254, 2023). "Taking together, higher levels of HTR1B and ALKBH5 in the blood of schizophrenia patients positively correlated with ERVWE1, and ALKBH5 was a novel schizophrenia risk gene." (PMID 37990254, 2023). "Herein, higher levels of HTR1B, Arc, and ALKBH5 were detected in schizophrenia patients compared with the healthy controls and had a positive correlation with ERVWE1." (PMID 37990254, 2023). "HTR1B, ALKBH5, and Arc exhibited higher levels in individuals with first-episode schizophrenia compared to the controls and showed a strong positive correlation with ERVWE1." (PMID 37990254, 2023). "Further studies established that ERVWE1 impaired 5-HT plasticity through the HTR1B signal pathway in an ALKBH5-m6A-dependent manner in schizophrenia." (PMID 37990254, 2023). "Here, we reported that ALKBH5, an important demethylase of m6A, was significantly increased in the blood of schizophrenia." (PMID 37990254, 2023). "Consistently, we found elevated levels of ALKBH5 in both the whole peripheral blood mRNA (p < 0.01) and plasma protein (p < 0.001) in schizophrenia, indicating m6A modification dysfunction in schizophrenia." (PMID 37990254, 2023). "Strikingly, plasma HTR1B concentration also correlated significantly with plasma 5-HT, Arc, and ALKBH5 concentration in schizophrenia patients (r = − 0.6 in 5-HT, r = 0.6 in Arc, r = 0.7 in ALKBH5), indicating that HTR1B was associated with m6A modification in schizophrenia." (PMID 37990254, 2023). "Intriguingly, we discovered a positive correlation between HTR1B and the m6A demethylase ALKBH5 in schizophrenia patients (p < 0.05, correlation coefficient = 0.52), suggesting that aberrant expression of HTR1B might be associated with m6A demethylation." (PMID 37990254, 2023). "We first identified that ALKBH5 influenced mRNA stability in schizophrenia." (PMID 37990254, 2023). "Importantly, HTR1B, Arc, and ALKBH5 had a strong positive correlation with ERVWE1 in schizophrenia patients." (PMID 37990254, 2023). "We observed higher levels of HTR1B, Arc, and ALKBH5 in individuals with schizophrenia." (PMID 37990254, 2023). "Interestingly, HTR1B also showed positive correlations with ALKBH5 and Arc in schizophrenia." (PMID 37990254, 2023). "Taken together, ERVWE1 impaired neuronal plasticity in schizophrenia by activating the HTR1B signaling pathway in an m6A-dependent manner, and ALKBH5 was involved in these processes." (PMID 37990254, 2023). "In this paper, we demonstrated that ALKBH5 and HTR1B were increased in first-episode schizophrenia and displayed a strong correlation with ERVWE1." (PMID 37990254, 2023).
schizophrenia (continued). "Mechanistically, ERVWE1 upregulated HTR1B through ALKBH5-mediated m6A-dependent epigenetic modifications, contributing to the impairment of 5-HT neuronal plasticity by activating the ERK-ELK1-Arc signal pathway in schizophrenia." (PMID 37990254, 2023). "ERVWE1 impaired 5-HT neuronal plasticity in ALKBH5-m6A dependent mechanism by the HTR1B-ERK-ELK1-Arc pathway, which may be an important contributor to aberrant synaptic plasticity in schizophrenia." (PMID 37990254, 2023). "Therefore, we proposed that ALKBH5 and HTR1B may serve as potential blood biomarkers for diagnosing and individualizing pharmacotherapy for patients with schizophrenia, highlighting a novel avenue for therapeutic targeting." (PMID 37990254, 2023).
α-thalassemia (1 paper, 2025). "According to their findings, the ALKBH5-mediated alteration of the m6A methylation status of BCL2A1 contributes to the pathogenesis of α-thalassemia." (PMID 40940799, 2025). "Specifically, they discovered that the expression of the MTase complex components METTL16, WTAP, CBLL1, RBM15B, and ZC3H13 was lower in this type of α-thalassemia compared to normal erythroid cells, whereas the eraser protein ALKBH5, as well as the readers IGF2BP2 and YTHDF3, were overexpressed." (PMID 40940799, 2025).
tumor (439 papers, 2016 to 2026). "In tumor-associated macrophages within colorectal cancer, ALKBH5 removes m6A marks from CPT1A mRNA, increasing its stability and expression, thereby promoting fatty acid oxidation and M2 polarization." (PMID 41376856, 2026). "Previous studies have shown that ALKBH5 plays a crucial role in m6A RNA modification and is closely associated with tumor progression and treatment resistance in various cancers 61-63." (PMID 40585991, 2025). "Taken together, ALKBH5 exerts context-dependent effects on MDSCs: it promotes tumor-associated immunosuppression via the Wnt/β-catenin-DKK1 axis, yet modulates autoimmune responses by stabilizing FoxO1 mRNA and regulating MDSC–T/B cell interactions." (PMID 41562066, 2025). "Meanwhile, ALKBH5 can recruit PD-L1-positive tumor-associated macrophages (TAMs) and promote M2 macrophage polarization by inducing the secretion of CCL2 and CXCL10, ultimately accelerating the progression of NSCLC." (PMID 40958857, 2025). "The interactions between ALKBH5 and reader proteins are closely associated with tumorigenesis and development, making them potential novel targets for tumor prevention and treatment." (PMID 40958857, 2025). "In previous studies, ALKBH5 has been implicated in promoting malignant phenotypes such as tumor proliferation, invasion, and migration." (PMID 39974663, 2025). "The synergy between ALKBH5 and IL-6 secreted by tumor-associated macrophages activates the JAK2/p-STAT3 pathway in cancer cells, promoting the progression of non-small cell lung cancer." (PMID 40585991, 2025). "To further explore the epigenetic mechanism underlying how ALKBH5 facilitates tumor progression and recognizes the downstream targets in SKCM, we performed RNA-Seq and MeRIP-Seq using shALKBH5 and negative control A375 cells." (PMID 38481816, 2024). "In the METABRIC dataset, low ALKBH5 mRNA expression was significantly associated with factors pertinent to poor prognosis including larger tumour size, high grade, and higher NPI (p < 0.05)." (PMID 39127986, 2024). "ALKBH5 is implicated in the proliferation, migration, invasion of cancer cell, and tumor metastasis." (PMID 38505602, 2024). "Overexpression of ALKBH5 significantly increases tumor-associated lymphangiogenesis and lymph node metastasis in vitro and in vivo." (PMID 39192357, 2024). "ALKBH5 and tumor-associated macrophage-secreted IL-6 showed a synergistic effect to activate the JAK2/p-STAT3 pathway in cancer cells." (PMID 38872221, 2024). "The AlkB homolog 5, RNA demethylase (ALKBH5), also known as ABH5, OFOXD, or OFOXD1, is implicated in the biological cascades of various neoplasms." (PMID 38501918, 2024). "ALKBH5 has been demonstrated to be necessary in facilitating the infiltration of tumor-associated microglia or macrophages (TAM) in vivo under hypoxic conditions." (PMID 38398118, 2024). "The immunosuppressive effect of TAMs allowed tumor progression and was partially rescued by IL-8 overexpression in ALKBH5-deficient GBM cells." (PMID 39198884, 2024). "ALKBH5 was found to recruit programmed death-ligand 1-positive tumor-associated macrophages and promote M2 macrophage polarization by inducing the secretion of CCL2 and CXCL10." (PMID 38872221, 2024). "As a tumor suppressor gene, the expression level of ALKBH5 is closely associated with tumor progression, patient prognosis, and therapeutic outcomes." (PMID 39192357, 2024). "ALKBH5 expression has also been shown to be increased in immortalised and transformed breast cell lines and tumour samples, and implicated in migration, invasion, and metastasis." (PMID 39127986, 2024). "Specifically, hypoxia can inhibit apoptosis not only by directly activating glycolysis but also cause tumor evasion of apoptosis by affecting EMT/ALKBH5 expression of EMT and angiogenesis-related transcripts." (PMID 39033180, 2024). "In pancreatic cancer (PC), ALKBH5 can regulate the tumor microenvironment, and its loss reduces the infiltration of CD8+ T cells in PC." (PMID 39295872, 2024).
tumor (continued). "Low ALKBH5 protein expression was significantly associated with unfavourable clinical parameters associated with tumour progression including larger tumour size and worse Nottingham Prognostic Index group." (PMID 39127986, 2024). "ALKBH5 overexpression increased tumor-associated lymphangiogenesis and LN metastasis both in vitro and in vivo." (PMID 36632222, 2023). "Compared to control mice, ALKBH5 knockdown enhanced the susceptibility of xenograft mice, as indicated by increased tumor growth rate and burden." (PMID 37612282, 2023). "The ITGB1-blocking antibody reduced the tumor metastasis caused by ALKBH5 overexpression and diminished lymphatic tube formation, EOC cell migration, and invasion." (PMID 36632222, 2023). "An enhanced therapeutic response to PD-1 inhibitor has also been observed in genetically mutated or ALKBH5 downregulated tumor cells, highlighting the pivotal role of ALKBH5 in the regulation of immune checkpoint therapy." (PMID 36810108, 2023). "ALKBH5 expression showed significant association with the infiltration of immune cells into the tumor microenvironment and immunotherapeutic response in multiple cancers." (PMID 35444654, 2022). "The results indicated that the expression of ALKBH5 shaped the immune conditions of tumor samples and, compared to the high-risk subgroup, the low-risk subgroup had a better immune microenvironment." (PMID 36686788, 2022). "This suggested that high ALKBH5 expression was associated with decreased infiltration of immune and stromal cells in several tumors, thereby resulting in high tumor purity." (PMID 35444654, 2022). "The expression of ALKBH5 is downregulated in colon cancer and is associated with tumor metastasis, and it is pointed out that this molecule can be used as an independent predictor of patient prognosis." (PMID 35614935, 2022). "ALKBH5 is an RNA demethylase that impacts RNA export and metabolism, and its aberrant expression is associated with the generation of tumours." (PMID 35414790, 2022). "Correspondingly, ALKBH5 shows a clear association with pro-tumor, cancer suppression, self-renewal ability of CSCs, autophagy, chemotherapy resistance, and other diseases." (PMID 35628623, 2022). "Compared to the normal tissue, we found almost all ALKBH homologous were associated with tumor stage except ALKBH5 and FTO." (PMID 35980268, 2022). "ALKBH5 has been found overexpressed in glioblastoma and its expression is associated with poorer prognosis, and it promotes GSCs proliferation and tumour progression by enhancing FOXM1 expression." (PMID 33461542, 2021). "Next, epigenetic analysis via LC-MS/MS reveals higher m6A-abundance in ALKBH5-deficient as compared to FTO-deficient B16 tumours, which meaningfully suppresses the expression of m6A-mediated ‘Mct4/Slc16a3’ in ALKBH5 alone and ‘Mex3d’ in ALKBH5 and FTO both." (PMID 34571899, 2021). "However, the function and underlying mechanisms of ALKBH5 in tumor development are still ambiguous and require further investigations." (PMID 40001461, 2025). "FTO and ALKBH5 demethylation may affect the expression of genes associated with autophagy in OC and contribute to tumor proliferation and invasion." (PMID 39904996, 2025). "A recent study reports that USP36, a deubiquitinating enzyme, is associated with and promotes ALKBH5 stabilization, thus contributing to tumorigenesis; in the same direction, ALKBH5 deficiency was suggested to represent an inhibiting factor for tumor proliferation in AML." (PMID 41020880, 2025). "Notably, ALKBH5 has been implicated in a series of studies as a tumor suppressor in NSCLC, and our results in the present study were in line with these findings." (PMID 39680684, 2025). "Furthermore, ALKBH5 downregulation is frequently observed in esophageal squamous cell carcinoma and is significantly associated with tumor progression and aggressive clinicopathological features, including advanced stage and metastatic potential." (PMID 40986143, 2025).
tumor (continued). "Studies have shown that in various types of cancer, low ALKBH5 expression is often linked to tumor deterioration and poor prognosis, while high ALKBH5 expression can significantly inhibit tumor cell proliferation, migration, and invasion, thereby slowing down tumor growth." (PMID 39192357, 2024). "Notably, ALKBH5 has been implicated in tumour progression, particularly in breast cancer, where it sustains the stemness of cancer cells as a major demethylase of m6A alterations." (PMID 39039912, 2024). "Thus, suggesting tumours with low ALKBH5 have an increased cytokine signalling causing pro-survival and pro-metastatic signals." (PMID 39127986, 2024). "In addition, altered ALKBH5 expression is closely associated with the onset and progression of various tumors and acts either as a tumor suppressor gene or as an oncogene, based on cancer types." (PMID 38545555, 2024). "Furthermore, ALKBH5 is closely associated with the occurrence and progression of tumors, and its expression level in tumor cells are related to prognosis and treatment outcomes." (PMID 39220683, 2024). "In TC, reduced ALKBH5 gene expression is associated with shorter overall survival times, indicating that ALKBH5 could suppress tumor progression." (PMID 37915103, 2023). "ALKBH5 promotes tumor-associated lymphangiogenesis and then LN metastasis, in which ALKBH5 stimulates downstream focal adhesion kinase (FAK)/Src proto-oncogene (Src) signalling and boosts integrin subunit beta 1 (ITGB1) expression by disrupting the YTHDF2 protein-mediated m6A degradation pathway." (PMID 36632222, 2023). "Consequently, ALKBH5-initiated CXCL8/IL8 induction improves tumor-associated macrophage infiltration and promotes tumor progression, demonstrating the impact of post-transcriptional epigenetic modifications in regulating the immunosuppressive GSC phenotype." (PMID 36212415, 2022). "Besides, from the analysis results of clinicopathological features, high expression of YTHDF1 was associated with advanced pM stage and tumor size >5 cm, while high expression of ALKBH5 was negatively associated with vascular invasion." (PMID 36347025, 2022). "Given that ALKBH5-deficient GBM demonstrated a sharper rate reduction in tumor growth and better survivability in C57 than in NSC mice, we hypothesized that ALKHB5 would influence the antitumor function of the immune system." (PMID 36566230, 2022). "The nomograms were constructed by combining all the independent prognostic markers, namely, tumor grades, ALKBH5 mRNA expression levels, IDH mutation status, 1p/19q codeletion status and MGMT promoter status, based on the results of the Cox regression analysis." (PMID 35444654, 2022). "Importantly, ALKBH5 deletion enhanced the efficacy of anti-PD-1 therapy and significantly prolonged the survival of ALKBH5-deficient tumor-bearing mice." (PMID 35628623, 2022). "Moreover, upregulation of YAP or downregulation of mature miR-181b-5p displayed a remarkable attenuation of anti-tumor activities caused by ALKBH5." (PMID 33431791, 2021). "We found that the copy number loss of ZC3H13, FTO, YTHDC2, WTAP and ALKBH5 decreased the protein expression in tumor samples, and meanwhile, patients with amplification of IGF2BP3, HNRNPA2B1 and IGF2BP2 presented higher expression level of these three proteins than normal tissues." (PMID 32710725, 2020). "Interestingly, the upward trend in ALKBH5 was significantly associated with tumor recurrence when we compared primary and recurrent tumors." (PMID 32211315, 2020). "Furthermore, we uncovered the underlying mechanism of 6PGD in promoting tumor growth and metastasis, which binds to ALKBH5 and inhibits the activity of ALKBH5, resulting in the increase of m6A modifications of MDM2 mRNA and the subsequent increase of its mRNA stability mediated by YTHDF2." (PMID 40611205, 2025).